MMP13 (matrix metallopeptidase 13)
Diseases named in the same sentence as MMP13 in open-access papers (continued):
Sharing a sentence is not in itself a finding about the gene and the disease.
osteosarcoma (42 papers, 2011 to 2025). A usually aggressive malignant bone-forming mesenchymal neoplasm, predominantly affecting adolescents and young adults. "According to the literature, JNK activation is associated with decreased proteoglycan synthesis and enhanced MMP13 expression and is linked to osteoblast proliferation and development of osteosarcoma." (PMID 35406794, 2022). "Of particular note, MMP-13 is reported to be associated with the invasion ability of osteosarcoma, and thyroid cell carcinoma." (PMID 33723319, 2021). "In conclusion, upregulation of PAI‐1 in human osteosarcoma cells is correlated with an increased risk of lung metastasis via an elevated level of MMP‐13 expression." (PMID 26817521, 2016). "Using C28/I2 chondrocyte cells, we have shown that silencing Rac1 by siRNA reduces the activation of p38 MAPK, which is reported to be linked to the upregulation of MMP13 by inflammatory cytokines and in osteosarcomas." (PMID 24180431, 2013). "Metastatic osteosarcoma is caused by the upregulation of MMP-13." (PMID 39456416, 2024). "Elevated levels of MMP-13 are intricately connected with more metastatic behavior, and miR-143 directly downregulates this enzyme to limit Osteosarcoma cell invasion." (PMID 40429954, 2025). "Additional predicted targets of miR-30a and miR-30e within this pathway include PIK3CA, mTOR, FOXO3, MMP13, SOX9, BCL2, VEGFA, and CCND1, all of which have been previously associated with osteosarcoma pathogenesis." (PMID 40862758, 2025). "In our study, Tas and PCI significantly suppressed MMP9 and MMP13 expression, leading to reduced osteosarcoma cell migration and invasion, as evidenced by the wound healing assays." (PMID 40332124, 2025). "The increased invasion and lung metastasis of human osteosarcoma cells are attributed to elevated MMP-13 expression and release." (PMID 38612399, 2024). "In the present study, we demonstrated that Vitex suppressed cell migration in a wound-healing assay, inhibited the invasion of human osteosarcoma cells and suppressed the expression of MMP-13 in human osteosarcoma cells." (PMID 38612399, 2024). "IL-32 stimulates the invasion and metastasis of osteosarcoma cells through MMP-13 expression mediated by the AKT pathway." (PMID 38584169, 2024). "The downregulation of MMP-13 is also identified as a crucial mechanism decreasing osteosarcoma cell migration and invasion." (PMID 37893141, 2023). "It has been proven that miRNA has direct or indirect effects on osteosarcoma, such as targeting matrix metalloproteinase 13 (MMP13) and B cell CLL/lymphoma 2 (Bcl-2)." (PMID 35111226, 2022). "The downregulation of MMP-13 by injected MicroRNA-143 in highly metastatic human osteosarcoma cells, 143B, significantly suppresses lung metastases, but the proliferation potential remains the same." (PMID 32377334, 2020). "In osteosarcoma, NNT-AS1 can sponge miR-320a and up-regulate the expression of β-catenin, RUNX2, p-AKT, insulin-like growth factor type 1 receptor (IGF1R), MYC, cyclin D1, and MMP-13, thereby promoting osteosarcoma cell growth and tumor development." (PMID 33113895, 2020). "MMP-13 (also known as collagenase-3) secreted by osteosarcoma cells has been found to be another important molecule for the ability of tumour cells to invade the extracellular matrix and induce lung metastases." (PMID 32377334, 2020). "Studies have revealed that MMPs including MMP-1, MMP-2, MMP-3, MMP-7, MMP-9, MMP-12, and MMP-13 are significantly related to osteosarcoma metastasis and poor prognosis." (PMID 33228783, 2020). "Conversely, upregulation of MMP-13 and stimulation of the AKT-pathway mediated by MMP-13 by Interleukin-32 enhances the motility and invasion of osteosarcoma cells, confirming the key role of this metalloproteinase in lung metastases." (PMID 32377334, 2020). "In line with the pro-metastatic role of PAI1, it has been shown to facilitate invasion and lung metastasis in osteosarcoma cells by promoting MMP13 expression and secretion." (PMID 32344898, 2020).
osteosarcoma (continued). "In the present study, we showed that SK-216, a PAI-1 inhibitor, suppressed the invasion and lung metastasis ability of human osteosarcoma cells through the reduction of MMP-13 secretion." (PMID 29510576, 2018). "Further study is needed to clarify the mechanism by which PAI‐1 regulates MMP‐13 expression in human malignancies, at least in human osteosarcoma." (PMID 26817521, 2016). "While miR-9’s regulation of MMP-13 (matrix metalloproteinase-13) remains less well-documented in Osteosarcoma, its influence on other metalloproteinases, such as MMP-2 and MMP-9, underscores its capacity to degrade the extracellular matrix and promote invasion." (PMID 40429954, 2025). "SpiA also decreased VEGF and MMP-13 protein levels in human osteosarcoma cells." (PMID 39456416, 2024). "Additionally, the downregulation of MMP-3 and MMP-13 can decrease osteosarcoma cell migration and invasion." (PMID 37893141, 2023). "Several studies have shown that osteosarcomas with high MMP13 expression have poor outcomes." (PMID 36428766, 2022). "Moreover, HCG11 promotes the expression of MMP13 and exacerbates osteosarcoma through sponging miR-579." (PMID 35359458, 2022). "Additionally, MMP-2, MMP-9, and MMP-13 overexpression has been revealed to be a promising indicator for osteosarcoma prognosis and pulmonary metastasis." (PMID 33228783, 2020). "Likewise, TCS downregulated parathyroid hormone- (PTH-) or PGE2-stimulated matrix metalloproteinase-13 (MMP-13) expression in rat osteoblastic osteosarcoma cells." (PMID 31191794, 2019). "Furthermore, PAI-1 was reported to promote tumor metastasis via upregulating MMP13 expression and secretion in osteosarcoma." (PMID 31170987, 2019). "Moreover, co-transfection of Runx2 with the Mmp13 promoter in osteosarcoma UMR 106–01 cells has been shown to enhance Mmp13 promoter activity." (PMID 28539595, 2017). "Our findings indicated that PAI‐1 and MMP‐13 might be available metastasis‐prediction markers and also valuable target genes for preventing lung metastasis of osteosarcoma." (PMID 26817521, 2016). "Downregulation of miR-143 promotes osteosarcoma cell invasion through MMP-13 upregulation, and silencing of miR-133a reduces the malignancy of CD133high osteosarcoma-initiating cell population through restoring the expression of multiple target genes (SGMS2, UBA2, SNX30, and ANXA2)." (PMID 25912304, 2015). "The relevance of this phenomenon in cancer has been shown for the genes MMP13, Birch2, and Birch3, which are functionally related oncogenes contained on the same amplification in osteosarcoma, and for BIRC2 and YAP1, cooperating oncogenes in an amplification in hepatocellular carcinomas." (PMID 23393560, 2013). "Moreover, MMP13 interacts with other MMPs to form a network for osteosarcoma genes." (PMID 38966281, 2024). "We finally immunohistochemically evaluated the expression of PAI‐1 and MMP‐13 in 52 human primary osteosarcoma samples in order to determine whether the expression pattern of the two proteins is correlated with lung metastasis of osteosarcoma cells." (PMID 26817521, 2016). "The observed reduction in osteosarcoma cell migration was corroborated by the molecular analysis of ECM-degrading enzymes, particularly MMP9 and MMP13." (PMID 40332124, 2025). "MMP13, MMP2, and MMP14 have been identified to interact with each other and to promote the progression and invasion of osteosarcoma." (PMID 38966281, 2024). "IFITM5, MMP13, PANX3, and MAGEA6 were some of the most overexpressed genes in osteosarcoma samples, while SLC4A1, HBA1, HBB, AQP7 genes were some of the top downregulated genes." (PMID 38966281, 2024). "To identify the mediator of MCP-1-promoted osteosarcoma migration, we further examined the expression of MMP-1, MMP-2, MMP-3, MMP-7, MMP-9, MMP-12, and MMP-13 mRNA under MCP-1 stimulation." (PMID 33228783, 2020).
osteosarcoma (continued). "To identify the mediator of TSP‐2‐promoted osteosarcoma migration, we examined levels of MMP‐1, MMP‐2, MMP‐3, MMP‐7, MMP‐9, MMP‐12 and MMP‐13 mRNA expression following TSP‐2 stimulation." (PMID 33021341, 2020). "This study showed that knockdown of PAI‐1 expression using siRNA‐mediated suppression resulted in a decrease in MMP‐13 expression and secretion in 143B cells, suggesting that MMP‐13 expression is regulated by PAI‐1 in osteosarcoma cells." (PMID 26817521, 2016). "For instance, in osteosarcoma, high expression of CCN3 is significantly correlated with poor prognosis, and CCN3 may increase cell motility and MMP-13 expression through the integrin-dependent pathway." (PMID 29061995, 2017). "Ectopic expression of WWOX in different osteosarcoma cell lines inhibits metastasis, and the expression of RUNX2 and its target genes such as VEGF (vascular endothelial growth factor gene) involved in angiogenesis and MMP13 (matrix metalloproteinase-13 gene) involved in invasion." (PMID 33946771, 2021). "However, the mechanism by which PAI‐1 regulates MMP‐13 expression in osteosarcoma cells has not been clarified." (PMID 26817521, 2016). "However, IL-32 did not affect MMP-2 and MMP-9 expression in osteosarcoma cells whereas MMP-13 is involved in the IL-32-induced migration, suggesting that different types of proteases affects the migratory processes in a cell-type specific manner." (PMID 27589563, 2016).
periodontitis (35 papers, 2012 to 2025). An acute or chronic inflammatory process that affects the tissues that surround and support the teeth. "MMP-8 (–799C/T) and MMP13 (–77A/G) can be associated with chronic forms of periodontitis in the Indian population." (PMID 39553301, 2024). "The indication of MMP-13 expression in alveolar bone loss has been proposed as a characteristic of periodontitis progression." (PMID 38699090, 2024). "This study has assessed the potential involvement of MMP-13 gene polymorphisms in individuals with periodontitis compared to healthy individuals." (PMID 38699090, 2024). "MMP9 is one of the major collagen-degrading enzymes in saliva, which is associated with periodontitis and MMP-13 has also been found to be involved in periodontal tissue destruction and alveolar bone resorption." (PMID 37047877, 2023). "In this way, MMP-8 and MMP-9 are extremely valuable diagnostic tools in treating periodontitis, while MMP-13 affects the activity of osteoclasts and bone resorption, contributing to the destruction of the periodontal tissue." (PMID 37047877, 2023). "MMP-13 has been associated with the destruction and resorption of bone and cartilage in periodontitis, being responsible for the activity of osteoclasts." (PMID 35163727, 2022). "Although there is considerable research on the importance of MMP-13 in the progression of periodontal disease, the exact mechanisms of association of periodontitis with this metalloproteinase are still unclear." (PMID 35163727, 2022). "A few articles have reported the relation of MMP-12 −357 Asn/Ser as well as MMP-13 −77 A/G and 11A/12A SNPs to periodontitis risk in Caucasian population." (PMID 27194818, 2016). "MMP-12 −357 Asn/Ser as well as MMP-13 −77 A/G and 11A/12A SNPs, located on 11q22.2-q22.3 chromosomes, has been evaluated with the periodontitis risk in a limited number of studies." (PMID 27194818, 2016). "The association between gene polymorphisms in chronic periodontitis and response to treatment was examined in patients that presented a susceptible genotype in the following genes IL-1, IL-4, IL-8, MMP-13, MMP-1 and MBL." (PMID 26595831, 2016). "Conducting such studies could provide insights into the potential relevance of MMP-13 gene polymorphisms and their correlation to periodontitis." (PMID 38699090, 2024). "In the present research, we examined the impact of MMP-13 (rs2252070) gene polymorphism on the predisposition to chronic periodontitis and explored the potential correlation between these genetic variations and chronic periodontitis in a southern Indian demographic." (PMID 38699090, 2024). "There is evidence indicating that MMP-13 may also cause alveolar bone destruction in periodontitis." (PMID 38699090, 2024). "Previous studies have shown the correlation of MMP-13 with increase in severity of inflammation in human periodontitis and different models of experimental periodontitis and that inhibition of MMP-13 reduced inflammatory bone resorption in vivo." (PMID 38152410, 2023). "Previous studies have demonstrated the relevance of MMP-2 and MMP-9 in periodontal diseases and increased MMP-13 activity in both murine model of periodontitis and human periodontitis." (PMID 38152410, 2023). "Our RNA-seq results showed upregulated MMP8 and MMP13 in periodontitis group, which were reported to be involved in the degradation of COL-I, COL-III and extracellular matrix observed in periodontitis." (PMID 37261355, 2023). "The detection of MMP-13 in gingival fluid showed increased levels of this proteinase in patients with chronic periodontitis compared to healthy subjects." (PMID 35163727, 2022). "MMP-13 expression level is increased in bacteria-induced periodontitis and the inhibition of MMP-13 expression decreases bone resorption and the production of inflammatory mediators." (PMID 36142454, 2022). "It was reported that in periodontitis patients, MMP-13 induces pro-MMP-9 activation in gingival tissue." (PMID 31340803, 2019).
periodontitis (continued). "A previous study from our group reported that MMP-13 induces proMMP-9 activation in gingival tissues from periodontitis patients." (PMID 28218665, 2017). "Collagenase levels of MMP-14, MMP-8, and MMP-13, have been correlated in chronic periodontitis patients, which suggests either a co-operative role and/or the potential settlement of collagenase activation cascades." (PMID 28218665, 2017). "MMP-14 can activate MMP-8 and -13 in vitro, as well as MMP-2, and has been correlated in vivo with active MMP-13 in periodontitis sites." (PMID 28218665, 2017). "MMP‐13, however, was almost undetectable in serum; very low concentrations were registered particularly in the periodontitis patients." (PMID 29744196, 2017). "Therefore, this study assesses the genetic link between the MMP-13 (rs2252070) genetic variation and chronic periodontitis in a Southern Indian demographic." (PMID 38699090, 2024). "Our results indicate that the MMP-13 polymorphism is not linked to periodontitis in the examined population." (PMID 38699090, 2024). "MMP8 and MMP13 are generally acknowledged to be the most rewarding salivary biomarkers for the diagnosis of periodontitis, which are crucial proteases that regulate gingival destruction and alveolar bone destruction in periodontitis." (PMID 37261355, 2023). "In addition, matrix metalloproteinase-8 (MMP-8), matrix metalloproteinase-9 (MMP-9), and matrix metalloproteinase-13 (MMP-13) are present in higher levels in the saliva of individuals with periodontitis than in the saliva of healthy individuals." (PMID 35048079, 2021). "Moreover, MMP-13 expression was also observed in gingival sulcular epithelium, macrophage-like cells, and gingival fibroblasts and plasma cells in chronic periodontitis." (PMID 29054963, 2017). "Additionally, MMP-13 (collagenase-3) expression was found in GCF samples from patients with chronic periodontitis, and its activity in these samples was significantly elevated." (PMID 29054963, 2017). "Moreover, protein localization of MMP-13, which was up-regulated by IL-1Ra KO in Ca9-22 cells, was examined by immunohistochemistry in an experimental periodontitis model of IL-1Ra KO mice." (PMID 26474296, 2015). "Furthermore, infection with Aggregatibacter actinomycetemcomitans to establish an experimental periodontitis model resulted in predominant localization of MMP-13 along apical junctional epithelial cells." (PMID 26474296, 2015). "Previous works support that MMP -2, MMP-9 and MMP-13 play important roles in both, the initiation and progression of inflammatory bone resorption and soft periodontal tissue breakdown during pathological processes, including chronic periodontitis." (PMID 22436166, 2012). "Gelatine zymography and densitometric analysis were used to evaluate diseased gingival explants and draws the conclusion that the deterioration of both soft and hard supporting tissues as well as the activation of proMMP-9 during the development of chronic periodontitis may be related to MMP-13." (PMID 38420070, 2024). "Due to recent studies revealing that MMP-13 produced by mesenchymal cells plays a role in the loss of bone mass and because bone resorption is the hallmark of periodontitis, we then decided to investigate the role of CD73 in bone loss in our experimental model of ligature-induced periodontitis." (PMID 38152410, 2023). "Moreover, collagenase-3 (MMP-13) has been identified in GCF of subjects with periodontitis." (PMID 32481582, 2020). "In addition, the expression of MMP-9 and MMP-13 could be relevant predictive indicators for the progression of periodontitis." (PMID 33294463, 2020). "In addition, several MMPs are linked together where MMP-13 could be involved in the degradation of soft and hard support tissues and the activation of pro-MMP-9 during the progression of chronic periodontitis." (PMID 33294463, 2020).